GMDS-DT (GMDS divergent transcript)
Synonyms: GMDS-AS1
Gene: Long non-coding RNA gene on chromosome 6 (2,245,231 to 2,525,976, forward strand). Ensembl gene ENSG00000250903.
Diseases named in the same sentence as GMDS-DT in open-access papers:
GMDS-DT is named in the same sentence as 2 diseases in open-access papers, as found by Europe PMC text mining. Sharing a sentence is not in itself a finding about the gene and the disease.
GMDS-DT shares sentences with these, for which no sentence is quoted: cancer (1 paper); colon adenocarcinoma (1).